PCNA (proliferating cell nuclear antigen)
Diseases named in the same sentence as PCNA in open-access papers (continued):
Sharing a sentence is not in itself a finding about the gene and the disease.
cancer (continued). "To elucidate the functional role of EPO/EpoR signaling in cell proliferation and/or cell survival, we analyzed the effects of EPO stimulation on genes involved in the cell cycle, such as PCNA and CyclinD1, as previously observed in other cancer cell lines." (PMID 23052842, 2013). "This is mechanistically different from two small molecules that have recently been reported to bind PCNA and inhibit cancer cell growth by interfering with PCNA’s function during replication." (PMID 23936203, 2013). "It has been demonstrated that certain cancer cells are stressed as a consequence of their genomic mutations, and it is thus possible that the total PCNA in these cells contains more of a modified PCNA with high affinity for APIM-peptides that could sensitize these cancer cells to ATX-101 treatment." (PMID 23936203, 2013). "To assess the biological behavior of various squamous lesions, we performed immunohistochemical staining for PCNA because the proliferative index is often increased in dysplastic and cancer tissues." (PMID 22272378, 2012). "H&E analysis was performed to identify the presence of cancer and hyperplastic conditions verified with the proliferation marker PCNA and the microvessel marker CD31." (PMID 23164239, 2012). "High percentages of precancerous and cancer cells exhibit increased cyclin D1, antigen identified by monoclonal antibody (Ki67), proliferating cell nuclear antigen (PCNA), phosphorylated ERK1/2 and phosphorylated STAT5." (PMID 24575359, 2012). "In this study we examined the details of PCNA polyubiquitination in normal human fibroblasts and cancer cell lines." (PMID 20353596, 2010). "SRC1-/- tumors showed significantly decreased numbers of PCNA positive cells compared to SRC1+/+ cancers (6% vs. 70%; p < 0.0002)." (PMID 21080969, 2010). "Our results indicated that the mammary epithelial cells from cancer-bearing TA2 mice had a higher proliferation index (PCNA labeling index) than those of the five-month-old TA2 mice, and this was further confirmed by real-time PCR." (PMID 20092659, 2010). "In our previous study we demonstrated that disruption of RAD18 abrogates PCNA polyubiquitination in several cancer cell lines after UV irradiation." (PMID 20353596, 2010). "The lower the target temperature of RFA was, the higher was the expression of MMP-9, VEGF and PCNA in residual hepatic VX2 carcinoma tissues." (PMID 20667141, 2010). "It follows from a comprehensive statistical analysis that a number of antigens such as hTERT, PCNA and Ki-67 can be considered as cancer markers, while another set of antigens such as P27KIP1 and FHIT are possible markers for normal tissue." (PMID 18366613, 2008). "The process of PCNA gene induction is likely to be essential to the mitogenic effects of E2 in some ERα-expressing cancers." (PMID 18949048, 2008). "GnT-V immunoreactivity was detected at variable levels, and was found in the cytoplasm of cancer cells, which were identified using PCNA co-staining." (PMID 17971775, 2007). "In 20 of 24 patients, the protein content ofc-Myc and of PCNA in cancer specimens was above that in mucosaspecimens." (PMID 17389773, 2007). "Amongst the various methods available, two important methods of studying cancer cell proliferation are measuring the rate of DNA synthesis and the immunohistochemical reaction for proliferating cell nuclear antigen (PCNA)." (PMID 16092956, 2005).
cancer (continued). "Patients with PCNA-positive carcinomas had significantly shorter survival times than patients with PCNA-negative carcinomas (median survival times: 51 vs 89 weeks)." (PMID 10817513, 2000). "Stage I borderline tumours had significantly lower PCNA labelling indexes than stage I malignant tumours (P < 0.048)." (PMID 7841053, 1995). "This suggests that targeted inhibition of PCNA expression or activity may be an effective strategy to inhibit cancer cell proliferation." (PMID 40313621, 2025). "These first-in-class compounds marked a significant step forward in PCNA-targeted cancer therapy." (PMID 41170373, 2025). "Moreover, elevated PCNA expressionwas linked with increased sensitivity to several drugs, particularlyto Navitoclax, NPK76-II-72-1, and Ciclopirox across cancers." (PMID 40657100, 2025). "Moreover, PCNA has been proposed as a cancer therapeutic potential by targeting its DNA damage repair function to induce synthetic lethality." (PMID 41301803, 2025). "The theoretical pan-cancer applicability of PCNA inhibition is exceptionally high, driven by the protein’s universal overexpression in malignancies and its fundamental role in DNA replication and repair processes essential for all proliferating cancer cells." (PMID 41170373, 2025). "PCNA is a human sliding clamp protein that plays a crucial role in DNA replication and repair, making it an ideal therapeutic target for proliferative diseases such as cancer." (PMID 40051490, 2025). "The expression of specific cancer-associated PCNA (caPCNA) isoforms, which are not uniformly present across all malignancies, creates an additional layer of differential susceptibility, as inhibitors like AOH1996 are designed to target these variant forms." (PMID 41170373, 2025). "Thus, the ultimate goal is not mere inhibition, but rather the exceptionally refined task of achieving selective disruption of cancer-specific PCNA interactions." (PMID 41170373, 2025). "AOH1160 is a PCNA inhibitor that can selectively kill many types of cancer cells at below micromolar concentrations through specifically targeting the L126-Y133 region of PCNA in cancer cells, without causing significant toxicity to a broad range of nonmalignant cells." (PMID 40313621, 2025). "Phosphorylation of PCNA at tyrosine 211 (pY211) has been identified as a marker of cancer progression and could serve as a predictive biomarker for inhibitors targeting this modification (Wang YL." (PMID 41170373, 2025). "In addition, PCLAF is involved in DNA damage repair by interacting with proliferating cell nuclear antigen, which is advantageous for cancer cells’ resistance and survival in genotoxic treatments like radiation and chemotherapy." (PMID 41035818, 2025). "As this study progresses, the scientific community eagerly anticipates the results of these studies, which could validate the therapeutic potential of AOH1996 and transform PCNA from an “undruggable” target into a cornerstone of cancer therapy." (PMID 41170373, 2025). "The present studyis a pioneering effort to conduct a pan-cancer analysis on PCNA, aimingto holistically comprehend the multidimensional role of PCNA in cancerpathology and advocate it as a potent therapeutic candidate for synergistictherapies to enhance intervention and longevity." (PMID 40657100, 2025). "Additionally, PCNA can interfere with immune regulation by interacting with natural killer (NK) cell inhibitory receptors on cancer cell surfaces, suppressing NK cell-mediated cytotoxicity and promoting immune escape." (PMID 40430573, 2025). "Similarly, Panax notoginseng saponins have been found to reduce Ki67 and PCNA expression, thereby inhibiting cancer cell proliferation." (PMID 39906672, 2024). "Cancer-specific PCNA inhibition may allow the use of oncolytic viruses alongside PCNA inhibition which could potentially unleash a new treatment modality." (PMID 39205238, 2024). "PCNA and Ki67 are common proliferative biomarkers used in cancer." (PMID 38383342, 2024).
cancer (continued). "Indeed, Ki67 and PCNA are widely utilized in pathology analyses to predict cancer activity and prognosis." (PMID 39594777, 2024). "PCNA is widely regarded as an effective marker for detecting cancer cell proliferation." (PMID 38710918, 2024). "These include: (A) the knockdown or overexpression of Grx2 in cells, and combination with drug treatment; (B) the relationship between PCNA and Grx2 (which is upregulated and which is downregulated) in cancer cells; and (C) investigating the functional significance of Grx2 in serum." (PMID 38256132, 2024). "Proliferating cell nuclear antigen (PCNA) is also a key marker of cancer cell proliferation." (PMID 38474142, 2024). "Indeed, PCNA demonstrates similar post-translational modifications between normal and cancer cells, with the only significant difference being that the protein level of PCNA is several-fold higher in cancer cells." (PMID 39205238, 2024). "Additionally, the protein levels of Ki67 and PCNA, the proliferating indicators of cancer, were found to be greatly reduced in the UTP11 knockdown samples." (PMID 38233795, 2024). "However, reports on this are sparse and there is a suggestion that the difference in isoforms described is a combination of the different efficiencies of the anti-PCNA antibody used and the different protein levels of PCNA in cancer and normal cells." (PMID 39205238, 2024). "The results indicate that varying solanine concentrations (10, 20, and 30 μM) considerably reduce the expression of iNOS, IL-6, cyclin-D1, and PCNA proteins in KB-ChR-8-5 cells, suggesting that solanine has the ability to significantly decrease the formation of malignant tumors." (PMID 39124760, 2024). "We integrated analyzed the function of P4HA3 among 33 types of cancers, and found that P4HA3 was associated with proliferation markers (PCNA and MKI67), EMT markers (VIM, TWIST1, SNAI1, SNAI2, FN1 and CDH2), extracellular matrix (ECM) markers (MMP9, MMP7, MMP2 and MMP14)." (PMID 39504328, 2024). "PCNA is an essential factor in cell cycle progression with high expression in cancer cells." (PMID 39061949, 2024). "PCNA is a target for anti-cancer drugs and β-clamp a target for antimicrobial drugs." (PMID 38814467, 2024). "Moreover, it was confirmed that Ki67 and PCNA act as proliferation markers in several malignant tumors." (PMID 38591121, 2024). "Authors concluded that in addition to anti-cancer treatments, perhaps targeting PCNA may provide a novel was of treating HSV-1 infection." (PMID 39205238, 2024). "Socioeconomic status has also been linked to cancer prognosis after studying the presence of PCNA+ TAMs in Caucasian and non-Caucasian populations." (PMID 39205238, 2024). "Cyclosporin A can inhibit the proliferation of cancer cells, possibly by controlling the expression levels of c-Myc, p21, and proliferating cell nuclear antigen (PCNA) through the suppression of calcineurin (CaN)/nuclear factor of activated T cells (NFAT) activity." (PMID 39411137, 2024). "Interestingly, a large fraction (~70%) of the efficient patient population with advanced cancer had stable disease at the end of the study, indicating the biological activity of targeting the PCNA-regulated stress responses." (PMID 39682151, 2024). "Furthermore, a reduction in the mRNA levels of intracellular OCT4 and PCNA was observed in PLB-treated cancer cells, accompanied by an increase in KLF4 mRNA activation." (PMID 39275349, 2024). "Aberrant expression of MAGEA4 in cancer cells may encourage PCNA monoubiquitination and the recruitment of error-prone polymerases, even in the absence of DNA damage, through the stabilisation of RAD18." (PMID 38448672, 2024).
cancer (continued). "Similarly, ATX-101 demonstrates the capacity of CPPs to enhance the efficacy of DNA-damaging agents by disrupting PCNA, a critical protein involved in DNA repair and cell survival, thus sensitizing cancer cells to chemotherapy." (PMID 39795861, 2024). "Notably, the inhibitory effect on the chick chorioallantoic membrane (CAM) cancer models was confirmed by the reduction of the expression of both PCNA mRNA and capsase-3 protein active form." (PMID 38644364, 2024). "It has been suggested that this post translational modification of PCNA could be used as a biomarker for early detection of cancer." (PMID 39205238, 2024). "Suppression of PCNA may lead to an increase in innate immune function (through activation of NK cells and macrophages) in addition to a decrease in cancer cell growth (through inhibitors of DNA replication at the level of the replication fork)." (PMID 39205238, 2024). "Targeting the PCNA–p15 interaction is a promising therapeutic strategy against cancer." (PMID 37511614, 2023). "Moreover, we observed significant cancer cell death, accompanied by a reduction in mRNA levels of the cell proliferation marker, proliferating cell nuclear antigen (PCNA), following ERK5 inhibition due to MHJ-627 treatment." (PMID 37504304, 2023). "The downregulation of Annexin A2 has been reported in several cancers (esophageal squamous cell carcinoma, oral squamous cell carcinoma, and prostate cancer), and might have an effect on PCNA migration to the membrane." (PMID 37686697, 2023). "PCNA is considered to be a marker of cell proliferation in various cancers." (PMID 37511298, 2023). "A cell permeable peptide (R9-caPep) containing the L126-Y133 sequence of PCNA selectively blocks PCNA interactions in cancer cells and interferes with DNA synthesis and HR-mediated DSB repair, resulting in S-phase arrest, an accumulation of DNA damage, and an enhanced sensitivity to cisplatin." (PMID 37510250, 2023). "Because of PCNA’s fundamental role in cell growth, survival, and mutagenesis, many attempts have been made in recent years to therapeutically inhibit PCNA with promising results, demonstrating the potential of PCNA as a therapeutic target for cancer treatment." (PMID 37510250, 2023). "PCNA has been previously studied in cancer research and presents a viable target for antifungals." (PMID 37998903, 2023). "We’ve previously found a new marker called PCNA on the surface of various cancer cells." (PMID 37686697, 2023). "Specific inhibition of PCNA in cancer cells is an attractive anti-cancer strategy." (PMID 36564469, 2023). "The PCNA has been used as a widespread model in cancer studies and toxicity bioassays in teleost." (PMID 37076908, 2023). "The PCNA–p15 interaction presents a promising target for cancer therapy." (PMID 37511614, 2023). "A recent study also demonstrated the expression of PCNA on the cell surface of triple-negative breast cancer cells (TNBCs), which interact with NK cell receptors through NKp44, leading to the inhibition of the NK cell cytolysis function against cancer cells." (PMID 37686697, 2023). "Although the expression and interactions of CHAF1A and PCNA have been studied in other cancers, their roles in EC remain unclear." (PMID 37189802, 2023). "Among them, Y211 phosphorylation in PCNA preferentially promotes proliferation of cancer cells." (PMID 35628489, 2022). "However, royal jelly significantly decreased the PCNA level (P < 0.05) and prevented the cancer by inhibiting the proliferation." (PMID 35910834, 2022). "As the molecular mechanisms involved have been uncovered gradually, increasing numbers of informative biomarkers have been identified to evaluate the degree of malignancy of various cancers, including proliferating cell nuclear antigen (PCNA) and marker of proliferation Ki-67 (MKi67)." (PMID 36133906, 2022). "Thus, because of such strong roles in cancer progression, PCNA is considered as an effective target for the disease treatment." (PMID 36360296, 2022).
cancer (continued). "Therefore, PCNA is identified as a potentially valuable biomarker for cancer diagnosis and prognostic therapeutics." (PMID 35401213, 2022). "Hence, targeting PCNA using synthesized peptide molecules has led to a more profound impact on arresting cancer cell growth." (PMID 36430528, 2022). "PCNA, which may well indicate cancer cell proliferation activity, also decreased within tumors from Curcumol 80 mg/kg group (control group: 59.41 ± 8.56%; Curcumol 80 mg/kg group: 32.03 ± 8.97%)." (PMID 36467048, 2022). "Proliferating cell nuclear antigen (PCNA) is a marker of cell proliferation in various cancers." (PMID 36199546, 2022). "According to a former study, PCNA as an important oncogenic transcription biomarker and has been proven to play critical roles during evolution process of “inflammation–atypical hyperplasia–cancer”." (PMID 35946886, 2022). "Since we observed the overexpression of canonical PCNA in B-ALL, it could be that the PCNA transcript variants are also overexpressed in other cancer types." (PMID 36291073, 2022). "Thus, the overexpression of PCNA and Ki-67 is correlated with cancer progression, and targeting these nuclear antigens by melatonin has a remarkable inhibitory impact on HepG2 cell proliferation." (PMID 35141433, 2022). "Proliferating cell nuclear antigen (PCNA) is essential for DNA replication in cancer cells." (PMID 35628489, 2022). "PCNA is a biomarker that identifies the relationship between apnea and cancer." (PMID 35132330, 2022). "PCNA expression is upregulated in cancer cells compared to healthy normal cells and can be used as a target for the development of anti-proliferation and anti-cancer drugs." (PMID 36430528, 2022). "As a positive control for CRISPR competency, targeting of proliferating cell nuclear antigen (PCNA) by sgPCNA reduced the viability of the individual cancer cell lines included in this study, ruling out the possibility of incomparable genome editing efficiency." (PMID 36282572, 2022). "For instance, defects in pol ε, PCNA and RECQL4 lead to increased risk for cancer." (PMID 33477564, 2021). "Cotreatment with protein kinase G II and L-arginine inhibited the expression of PCNA in OC cells and was speculated to be a cancer inhibitor with a wide range of effects." (PMID 34721621, 2021). "Additionally, SHPRH‐146aa protects SHPRH from the degradation of the ubiquitin proteasome and promotes the ubiquitination of proliferating cell nuclear antigen (PCNA), reducing the malignant behavior of cancer cells in vivo and in vitro." (PMID 34097315, 2021). "In addition, the upregulation of PCNA expression is related to the degree of differentiation, International Federation of Obstetrics and Gynecology grade, lymph node metastasis, depth of cancer invasion, and human papilloma virus infection." (PMID 34721621, 2021). "Thus, we leaded a histopathological study of this component, along with additional cancer biomarkers such as PCNA, Ki67, and pH3." (PMID 34071030, 2021). "We propose that clarifying the regulation of PCNA PTMs may provide insights into understanding the development of cancers." (PMID 34671219, 2021). "As the half maximal inhibitory concentration (IC50) of PCNA-I1 in cancer cell growth (IC50, 0.17 ± 0.07 μM) is low enough compared to normal cell growth (IC50, 1.60 ± 0.36 μM), PCNA-I1 together with other PCNA-Is can be used as potential PCNA-targeted cancer therapies." (PMID 33498235, 2021). "PCNA is highly expressed in cancer cells and is critical for cellular proliferation." (PMID 34831131, 2021). "This shows PCNA inhibitors combined with other treatment may not only improve anti-cancer therapy effects but also compensate for the side effects of other anti-cancer drugs." (PMID 33498235, 2021). "However, the stronger colocalization of IGF-1R and PCNA is correlated to the higher overall survival in cancer patients." (PMID 34671219, 2021). "PCNA is highly expressed in squamous CC and is related to malignant tumors." (PMID 34721621, 2021).